BIRC5 (baculoviral IAP repeat containing 5)
Diseases named in the same sentence as BIRC5 in open-access papers (continued):
Sharing a sentence is not in itself a finding about the gene and the disease.
tumor (continued). "Additional in vivo experimentation in our study verified that NPs could enhance the radiosensitivity in vivo by down-regulating BIRC5 and up-regulating DR5, as witnessed by reduced tumor growth and down-regulated Ki67 positive expressions." (PMID 34372869, 2021). "Furthermore, BIRC5 expression was relatively high in advanced tumor stages in KIRC, KIRP, LIHC, LUAD and UCEC, and relatively low in advanced tumor stages in STAD." (PMID 33431968, 2021). "Moreover, LAF dramatically upregulated the levels of 14-3-3σ in tumour tissues and downregulated the levels of YAP and its regulatory proteins, including BIRC5, c-Myc and Bcl-2." (PMID 34010589, 2021). "In concordance with this, a difference in tumor size was not supported by analysis of BIRC5/survivin in the METABRIC and SCAN-B cohorts." (PMID 34064473, 2021). "Regardless of tumor stage, gender, age, smoking habits, and nodal metastasis status, BIRC5 transcription levels in tissues were significantly higher than in normal lung tissues." (PMID 34804966, 2021). "In contrast, there was no change (p > 0.05) in the expression of BIRC5 and Serpine-1 genes in tumor tissues from all treated groups when compared to the control group." (PMID 34371830, 2021). "The cell cycle (Cycling) program was characterized by high expression of genes involved in cell proliferation (e.g., CENPW, CKS1B, and BIRC5) and presented activation of the E2F targets, G2M checkpoint and MYC targets pathways, suggesting tumor cell proliferation." (PMID 34489433, 2021). "From the perspectives of tumor tissue and cell lines, we simultaneously found that BIRC5 and HK2 may increase tumor malignancy with MYCN amplification, whereas GRID2 and RNASEL were antagonistic to MYCN amplification." (PMID 34746127, 2021). "In contrast, Survivin/BIRC5 and TERT genes showed a prominent tumour-enriched expression." (PMID 32152425, 2020). "In addition, IHC results showed that normal liver tissue stained negatively or weakly positive for BIRC5 and ROBO1, while tumor tissue was high or medium positive." (PMID 33195412, 2020). "BIRC5 was found to upregulate VEGF expression in esophageal cancer cells, and may therefore potentially sustain tumor angiogenesis through VEGF signaling." (PMID 33614496, 2020). "Moreover, when samples were divided into six subgroups according to the tumor type, BL patients showed a significantly higher expression of both YY1 and BIRC5, if compared with less aggressive B-NHLs (including FL, MCL and MZL)." (PMID 32899428, 2020). "Multivariate cox proportional hazard analysis of DSS revealed that the combination of BIRC5 and KRT20 mRNA to predict outcome was an independent prognostic factor, when age, sex, BMI, tumor stage, grade, and node status were included in the analysis (p = 0.0167)." (PMID 33050010, 2020). "Importantly, through the use of the R2 platform, YY1 and BIRC5 expression levels were further compared in 12 independent B-NHL GEO datasets vs. normal control ones and found significantly higher in tumor specimens." (PMID 32899428, 2020). "The results show that BIRC5, CENPA, KIF4A, DTYMK, PRC1, and TRIP13 have low beta values in tumor." (PMID 32391055, 2020). "Furthermore, the overexpression of MALAT1 greatly increased the expression of BIRC5 yet downregulated the expression of miR‐203 in tumour tissues, indicating that MALAT1 sponged miR‐203 for the upregulation of BIRC5 (**P < 0.01)." (PMID 31250518, 2019). "Functional studies have reported that miR-483-3p may act as an oncogene by targeting BBC3/PUMA directly or tumor suppressor via repression of multiple targets including CDC25A, BIRC5, and RAN." (PMID 29717264, 2018). "BIRC5, a member of the anti-apoptosis family, mainly exerted its influence on HCC cells in inhibiting apoptosis, promoting proliferation, enhancing resistance to radiotherapy and chemotherapy and inducing the tumor stromal angiogenesis." (PMID 29707114, 2018).
tumor (continued). "Following this second hypothesis, we computationally found reliable interactions between UCA1 and the 3′-UTRs of ANLN, BIRC5, IPO7, KIF2A, and KIF23 that overlapped several miRNA-binding sites of tumor-suppressor miRNAs." (PMID 30195762, 2018). "In non-tumor tissues, 2 samples (4.9%) were exhibited positive BIRC5 expression, and 39 (95.12%) were negative." (PMID 29707114, 2018). "Moreover, FGF19 and BIRC5 were concomitantly overexpressed in all 10 of these tumour samples, further establishing a positive correlation between the expression of FGF19 and BIRC5, a STAT3 target gene, in human HCC." (PMID 28508871, 2017). "The mRNA levels of c-myc, Birc5, Cd44, Lgr5, Tcf7, Mmp7, and Ephb3 were significantly increased in tumor area compared with non-tumor area." (PMID 28710436, 2017). "Our past miRNA studies of BC cells showed that clustered miRNAs (including miR-1/133a (targeting TAGLN2), miR-23b/27b/24-1 (targeting EGFR, MET, and FOXM1), and miR-195/497 (targeting BIRC5 and WNT7A)) act as tumor-suppressive miRNAs through their regulation of several oncogenic genes and pathways." (PMID 27072587, 2016). "For instance, hsa-let-7b-5p is observed as tumor suppressive, the reason could be either or both: The targets of hsa-let-7b-5p included well-known oncogenes AURKA and BIRC5, or the targets involved much more amplified genes." (PMID 26099552, 2015). "By treating AdCC cell line with BIRC5 siRNA or YM155, a novel imidazolium-based compound, we observed a reduced cell proliferation, increase of apoptosis as well as autophagic cell death, which further demonstrates the tumor-promoting role of survivin in AdCC." (PMID 25485635, 2014). "Compared with the control group, adenovirus with Dual-shRNA exerted the strongest inhibitory effect on tumor growth because the tumor inhibitory rate was 67.59% (P = 0.0001) compared to 44.54% (P = 0.0020) and 25.25% (P = 0.0418) in the OCT4-shRNA and BIRC5-shRNA groups, respectively." (PMID 23433354, 2013). "This key observation indicates that the negative control of BIRC5 levels is a critical aspect of the tumor-suppressive activity of miR-203 in TNBC." (PMID 22713668, 2012). "In our study, we found an upregulation of Survivin/BIRC5 and Livin/BIRC7 in microdissected tumor-tissue and we could validate the dysregulation of Livin/BIRC7 by quantitative RT-PCR and IHC." (PMID 20808857, 2010). "BIRC5 showed affinity for anti-mitotic agents such as berberine, aligning with its function in cellular survival, whereas THY1 and FN1 were anticipated to engage with immune checkpoint inhibitors, reinforcing their promise in combinatorial therapy designed to augment anti-tumour immunity." (PMID 40475773, 2025). "Altered molecular targets, such as E-cadherin (CDH1), MMP9, Survivin (BIRC5), Cytokeratin 5 (KRT5), VEGFA, IL15, TNF-α (TNF), TRAIL (TNFSF10), and Tenascin-C (TNC), exhibited increased expression in our study, which correlates with their upregulation in tumor samples from individuals with OC." (PMID 40072102, 2025). "The observed difference in BIRC5 expression between cancerous and non-cancerous breast tissue may be attributed to the inclusion of non-tumor samples in the GTEx dataset, which can mask effects from the neoplastic microenvironment." (PMID 40725442, 2025). "However, in both TCGA and CBCS, BIRC5-high tumors were more common among Luminal B (LumB), Her2-enriched, Basal-like, ROR-PT-high and ER-negative tumor subtypes, as well as higher-stage tumors, and were more frequent among cases from Black women and younger women (< 50 years of age)." (PMID 38515208, 2024). "Therefore, we hypothesized that regulating IGF1, CDKN2A, BIRC5, and SPP1 levels may affect the tumor immune microenvironment in HCC." (PMID 39042294, 2024).
tumor (continued). "Collectively, our in-vitro results underscored the essential roles of PTPRT in inhibiting cell proliferation by affecting the expression of cell cycle-related genes like BIRC5, indicating that PTPRT downregulation could promote the malignant proliferation of tumour cells." (PMID 38216925, 2024). "To overcome this limitation, we analyzed TCGA data for ccRCC, pRCC, and chRCC and found that BIRC5 was significantly increased in tumors of the three major tumor subtypes compared with non-tumor tissues and that elevated expression correlated with tumor progression." (PMID 38203388, 2023). "Interestingly, in both tumor subgroups, we found a marked BIRC5 overexpression compared to the control samples, even though a very strong and significant positive correlation between HIF1A and BIRC5 was observed only in the KDM5CHigh subgroup." (PMID 36142158, 2022). "Furthermore, we found that BIRC5 was significantly correlated with the level of B cells, CD8+ T cells, CD4+ T cells, macrophages, neutrophils and dendritic cells, and was negatively correlated with tumor purity." (PMID 35309512, 2022). "The relative expression levels of CDKN3, MKI67, CEP55, SPAG5, AURKA, TOP2A were consistent with the results of bioinformatics analysis (P < 0.05), while the expression levels of UBE2C, CHEK1 and BIRC5 in tumor samples were not significantly different from adjacent normal samples." (PMID 35178291, 2022). "We found that the expression levels of UBE2C, CHEK1, and BIRC5 in tumor samples were not significantly different from adjacent normal samples, which may be due to the small sample size." (PMID 35178291, 2022). "BIRC5 is normally absent in mature cells but is distinctly overexpressed in tumor cells." (PMID 34150632, 2021). "Additionally, tumor suppressor miR-634 have also been found to be involved in development of 5-FU resistance by directly targeting a number of mitochondrial apoptosis pathway genes, such as OPA1, TFAM, LAMP2, APIP, XIAP, BIRC5, and NRF2." (PMID 34881242, 2021). "Il6 deficiency also reduced hepatic mRNA levels of Stat3 target genes (Birc5, Bcl2l1 and Ccnd1), cyclins (Ccna2, Ccnb1, Ccnb2), and markers of proliferation (Mki67) and HCC (Afp) in livers from FGF19-expressing mice, further demonstrating the role of IL-6 in mediating FGF19-driven tumour growth." (PMID 28508871, 2017). "Furthermore, BIRC5 overexpression results in EMT alteration and tumor aggressive growth." (PMID 29212257, 2017). "Moreover, we showed that the over-expression of miR-203 could suppress the proliferation and migration of TNBC cells, accompanied by a decrease in the expression of BIRC5 and LASP1, suggesting that miR-203 has tumor-suppressive effects in TNBC." (PMID 22713668, 2012). "Thus, a plasmid containing shRNA for the Birc5 gene could enter the cell, decrease Birc5 gene transcription in a targeted manner, promote tumor cell apoptosis, and reduce angiogenesis without affecting normal cells." (PMID 33233374, 2020). "Interestingly, from these 17 significant pairs (adjusted p-value ≤ 0.05) several downregulated tumour-suppressor miRNAs (e.g., miR-let-7c, miR-139, miR-145 or miR-195) appeared to regulate oncogenic genes related to the cell cycle and DDR pathways (BUB1B, AURKA, BIRC5, CENPK, BRCA1 and CHEK1)." (PMID 28387377, 2017). "First, although we explored the correlation between BIRC5 and immune infiltration in LGG patients, there is a lack of experiments to validation the function of BIRC5 in the tumor microenvironment regulation of LGG." (PMID 35309512, 2022). "5-Aza-CdR interestingly decreased levels of genes that promote tumor progression, such as CCND1, MKI67, BIRC5, and BCL2, but failed to decrease MUC4 and NOTCH1." (PMID 32182826, 2020).
tumor (continued). "The mRNA levels for several critical components of the pathway (BIRC5, CD44, FZD7, c-MET, MMP7, c-MYC, NOTCH1, PPARD, and VEGF) were significantly increased (DASL signal intensity) in TN tumor samples as compared to non-TN tumor samples." (PMID 24143235, 2013). "Activation of the canonical WNT pathway has been described to affect proliferation and migration of various non-rhabdomyomatous tumor cells through induction of the targets such as the pro-proliferative protein MYC and the pro-proliferative and anti-apoptotic IAP-protein BIRC5 (survivin)." (PMID 30568936, 2018).
infection (14 papers, 2010 to 2025). The state of being infected such as from the introduction of a foreign agent such as serum, vaccine, antigenic substance or organism. "The up-regulation of buffy (which encodes a pro-survival protein) and BIRC5 (belonging to the Inhibitor Apoptosis protein family) was observed after infection, shedding light on the pathways that these pathogens use to inhibit host cell apoptosis." (PMID 28152065, 2017). "Concurring with our hypotheses, the expression of BIRC5 can also lead to the progression of fibrosis or the susceptibility to infection." (PMID 37035748, 2023). "We found that HIV targeted cells in the FRT with high levels of BIRC5 for infection, and then further upregulated this protein." (PMID 32452381, 2020). "Infection with both microsporidia species up-regulates buffy and BIRC5, two genes with important function in programmed cell death." (PMID 28152065, 2017). "Both constructs targeting BIRC5 show similar reduction of cell viability at eight days post infection (BIRC5-B = 0.62 +/-0.1 and BIRC5-C = 0.69 +/- 0.14), whereas the construct HSPA8-A shows much weaker effects (0.86 +/-0.15)." (PMID 20051122, 2010). "PRE cells also expressed elevated levels of Blimp-1 and BIRC5, which may facilitate the ability of these cells to support productive infection by promoting HIV transcription and enhanced survival of the infected cells, respectively." (PMID 32452381, 2020). "Similarly, at this time point the transcript for an inhibitor of apoptosis, BIRC5 was increased 8-fold compared to the pre-infection expression level." (PMID 31937782, 2020). "It will be of interest to study BIRC5 expression at the protein level in these cells and to test the effects of a BIRC5 inhibitor such as YM155 on their ability to survive HIV-induced abortive infection." (PMID 35784348, 2022). "Moreover, MUG-Chor1 cells not only had high infection efficiency, but also the protein level of BIRC5 and DEPDC1B was significantly downregulated, which indicated that BIRC5 and DEPDC1B was knocked down successfully." (PMID 34330893, 2021). "Validation of the gene expression levels obtained by RNA-seq specific to the HCV group (BIRC5 and SLC22A1), the HBV group (CLEC1B), and the group without infection (FGFR4, HSF1, RNF187, HSP90AB1, and HSPB1) was performed using the real-time PCR technique." (PMID 36557005, 2022). "However, down-regulation of OCT4 expression inhibited BIRC5 expression, even in the OCT4-negative BEL-7404 cells, and increasing OCT4 expression by infection with adenovirus carrying the OCT4 gene in BEL-7404 cells up-regulated BIRC5 expression." (PMID 23433354, 2013).
adenocarcinoma (7 papers, 2018 to 2024). A common cancer characterized by the presence of malignant glandular cells. "Overexpressed in tumors, BIRC5 is associated with unfavorable overall survival in TN adenocarcinomas." (PMID 31093306, 2019). "In order to further evaluate the prognostic significance of BIRC5 in TN adenocarcinomas, the potential risk factors associated with OS of TN adenocarcinoma patients were analyzed using Cox regression analysis." (PMID 31093306, 2019). "Notably, only the overexpression of BIRC5 was associated with unfavorable overall survival (OS) in TN adenocarcinomas (log rank P = 0.0037)." (PMID 31093306, 2019). "It has already been shown that TS, nicotine in particular, upregulates BIRC5 expression in NSCLC possibly inducing an early developmental stage in adenocarcinoma CS compared to NS." (PMID 32564237, 2020). "We assumed that the oncogenic role and prognostic value of BIRC5 in TN adenocarcinomas can be ascribed to this “cell cycle-mediated” mechanism." (PMID 31093306, 2019). "Notably, compared with the previous investigations, our study provided new evidence that BIRC5 plays an important role in the prognosis of TN adenocarcinomas." (PMID 31093306, 2019). "BIRC5 is a potential predictor and therapeutic target in TN adenocarcinomas." (PMID 31093306, 2019). "The BIRC5 high-expression group had more male patients (P = 0.023) and smoked packs per year (P = 0.025), and TN adenocarcinoma patients in the BIRC5 high-expression group suffered from a significantly higher risk of distant metastasis (P = 0.046) and advanced N stage (P = 0.033)." (PMID 31093306, 2019). "In conclusion, for TN adenocarcinomas, BIRC5 may serve as a promising prognostic predictor and therapeutic target." (PMID 31093306, 2019). "These facts explained why BIRC5 was mainly involved in the regulation of cell cycle and apoptosis; meanwhile, it is supported in our study that the overexpression of BIRC5 promoted the development of TN adenocarcinomas, which may be via regulating the cell cycle signaling pathway." (PMID 31093306, 2019). "Among them, the mRNA expression of 5 genes, namely, BIRC5, MCM4, CDC20, KIAA0101, and TRIP13, were significantly upregulated among TN adenocarcinomas (all P < 0.05)." (PMID 31093306, 2019). "Then, using BIRC5 as a candidate, the prognostic value in LAD and TN adenocarcinomas was verified by the Kaplan-Meier plotter and The Cancer Genome Atlas (TCGA) database, respectively." (PMID 31093306, 2019). "In this study, we identified that the high level of mRNA expression of BIRC5 not only was related to unfavorable outcomes of LAD, but it also indicated a shorter OS of TN adenocarcinomas." (PMID 31093306, 2019). "Interestingly, when BIRC5/HIF1A/FLT4 were upregulated in LUAD tissues, they exhibited a high presence in solid pattern-predominant adenocarcinomas, which are large and aggressive tumors with poor prognoses." (PMID 37509650, 2023).
cardiovascular disease (3 papers, 2023 to 2025). "Birc5 has been shown to be upregulated in VSMCs in cardiovascular disease associated with arterial stiffening." (PMID 37868708, 2023).
gastrointestinal tumors (2 papers, 2020 to 2021). "BIRC5 promotes the progression of several gastrointestinal tumors, including HCC." (PMID 32391055, 2020). "Expression of the 4 autophagy-related genes (SQSTM1, BIRC5, NRG3, and CXCR4) can accurately predict the prognosis of gastrointestinal tumors in Asian patients." (PMID 34484469, 2021).
benign tumors (1 paper, 2008). "TOP2A, ETV4 and BIRC5 showed increased expression in all MPNST samples compared to the benign tumors, in most cases more than 20-fold, whereas HOXB7 showed approximately similar expression levels in the MPNSTs and the benign tumors." (PMID 18522746, 2008). "Within 17q, the genes topoisomerase II-α (TOP2A), ets variant gene 4 (E1A enhancer binding protein, E1AF) (ETV4) and baculoviral IAP repeat-containing 5 (survivin) (BIRC5) showed increased expression in all samples compared to two benign tumors." (PMID 18522746, 2008). "TOP2A, ETV4 and BIRC5 showed increased expression in all MPNST samples, in most cases more than 20-fold, whereas HOXB7 showed approximately similar expression levels in the MPNSTs and the benign tumors." (PMID 18522746, 2008).
CNS tumors (1 paper, 2024). "The most commonly overexpressed genes in CNS tumors included TOP2A (67%), BIRC5 (59%), CDK4 (50%), BRIP1 (49%), NOTCH1 (41%), SMO (39%), and TP73 (39%)." (PMID 38347552, 2024).
hematological neoplasms (1 paper, 2021). "All these studies support the association between STAT3 and resistance to apoptosis, and confirm an important role for Birc5 in hematological neoplasms and solid cancers." (PMID 33557010, 2021).